EZH2 (enhancer of zeste 2 polycomb repressive complex 2 subunit)
Diseases named in the same sentence as EZH2 in open-access papers (continued):
Sharing a sentence is not in itself a finding about the gene and the disease.
tumor (continued). "Since EZH2 plays a role in numerous immune cells that may contribute to tumor immunity, it is essential to investigate how inhibition of EZH2 may affect immune cell function during tumor development, a question that remains unanswered at present." (PMID 37069494, 2023). "However, enhancer of zeste homolog 2 (EZH2), a histone methyltransferase and a member of the polycomb group family is a relatively new biomarker, with limited published data on its significance in this tumor type." (PMID 38146588, 2023). "However, the efficacy of EZH2 inhibitors is limited due to EZH2’s multifunctional roles beyond its catalytic activity in certain cancers, where it can activate genes and contribute to tumor growth through alternative signaling pathways." (PMID 37752998, 2023). "Besides, SNHG6 may interfere with anti-tumor immune responses by affecting macrophages and cancer-associated fibroblasts in the tumor microenvironment, and may also promote KIRP progression by regulating the expression of molecules such as EZH2." (PMID 37004005, 2023). "In addition, knockdown of EZH2 impeded tumor growth through the FBXL7/PFKFB4 axis." (PMID 37179372, 2023). "Subsequently, EZH2 interacts with NF-κB to form the EZH2–p-p65-Ser536 complex, which binds to the IL-6 promoter and leads to the accumulation of immunosuppressive myeloid-derived suppressor cells (MDSCs), providing a tumor immunosuppressive microenvironment and inducing drug resistance." (PMID 36672374, 2023). "EZH2 in PCa cells may hasten tumor development and act as a tumor oncogene." (PMID 36884182, 2023). "Moreover, both tumor types appear to rely on residual EZH2 activity." (PMID 36759899, 2023). "Indeed, CCL2 was required for these anti-tumor immune effects, as CCL2 blockade reduced NK cell accumulation, abolished tumor regressions, and significantly mitigated the survival benefit and number of complete responders to combined EZH2 knockdown and T/P treatment." (PMID 37142692, 2023). "Moreover, cancer cell intrinsic and TME signals may account for the distinct effects of EZH2 inhibitor in different tumor types." (PMID 36900330, 2023). "Moreover, they also discovered that targeted EZH2 inhibition can reverse anti-tumor immunity." (PMID 38041084, 2023). "Additionally, EZH2 is closely connected to the tumor biological behaviors and patient prognosis." (PMID 38048186, 2023). "In addition, EZH2 expression promotes the immune escape of tumor cells." (PMID 37239949, 2023). "While the high selectivity of GSK126 has already been well confirmed and extensive studies in the tumor field suggest that the effect of GSK126 in treating tumors is through its inhibition of EZH2, additional EZH2 knockdown experiment may provide further evidence about the function of EZH2." (PMID 36768720, 2023). "Moreover, cluster 10 with high expression level of EZH2 had a function in tumor promotion." (PMID 37644609, 2023). "We analyzed the correlation of EZH2 and TOP2A with patients’ clinicopathological variables using HCC data from TCGA database and found that high EZH2 and TOP2A expression was significantly associated with tumor differentiation grade, tumor invasion, TNM stage, and the status of patients with HCC." (PMID 38008711, 2023). "Furthermore, lncRNA Snhg6, which is highly expressed in tumor-derived myeloid-derived suppressor cells (MDSCs), promotes the differentiation of CD11b+ Ly6G− Ly6Chigh monocytic (M)-MDSCs by stabilizing EZH2 through the protein ubiquitination degradation pathway." (PMID 37345170, 2023). "However, there are studies showing that EZH2 can also function as a tumor-suppressor." (PMID 35236381, 2022). "EZH2 may affect the antitumor effects of PARP inhibitors by remodeling the tumor microenvironment." (PMID 36263120, 2022).
tumor (continued). "We found most of these genes showed significantly elevated expression levels in tumor samples compared with adjacent normal (p-value = 5.38e−6, K–S test), and the tumor and normal samples were clearly separated, indicating that EZH2 could increase the transcriptional level of bound genes." (PMID 36578923, 2022). "HMTi blocks activity of EZH2 and may reinduce differentiation in neoplasia." (PMID 35814409, 2022). "For example, overexpression of wild-type (WT) EZH2, and subsequent increases in H3K27me3, have been described in several non-hematological cancers, including prostate and breast cancer, where evidence suggests that the increased H3K27me3 levels promote tumor progression and metastasis." (PMID 36359771, 2022). "Other factors, such as older age at diagnosis, higher tumour grade, and tumour multifocality identified as having strong associations with EZH2 at the univariate level, were not independently associated with a shorter disease-free interval at the multivariable level." (PMID 36292072, 2022). "Notably, preclinical studies have shown the concept that targeting both EZH1 and EZH2 can normalize the accumulation of H3K27me3 not only in high-grade tumor cells but also in cells in a precancerous state infected with HTLV-1 present in the peripheral blood of infected individuals." (PMID 35336993, 2022). "EZH2 may also be involved in PARP-associated DNA damage responses in tumor cells via a nonhistone methyltransferase catalytic pathway." (PMID 36263120, 2022). "Moreover, a connection was identified between EZH2 and tumor-infiltrating immune cells." (PMID 36195655, 2022). "Furthermore, EZH2 was related to the tumour immune microenvironment (TIME)." (PMID 35659256, 2022). "Interestingly, the treatment of mouse syngeneic tumor models with EZH2 inhibitors resulted in the accumulation of CD11b+Gr1+ cells in the tumor tissue, an increase in M1 macrophages with the consequent decrease in M2 macrophages, as well as a reduction in IFN-γ-producing CD8+ and CD4+ T-cells." (PMID 36135315, 2022). "Moreover, in altered H3K36 methylation settings, H3K27me3 would accumulate in regulatory elements of tumor suppressor genes due to EZH2-function, leading to their transcriptional repression, subsequently initiating poor cell differentiation, vascular invasion and tumor progression." (PMID 36230787, 2022). "Thus, direct modification of EZH2 by PARP1 may be involved in regulating the response of tumor cells to DNA damage and oxidative stress, but it remains unclear which downstream signaling pathways may be altered as a result of such modifications." (PMID 36263120, 2022). "Moreover, although inhibition of HIF1α, HDAC1, or EZH2 in immune cells can restore immune cytotoxicity, it also paradoxically induces PD-L1 and PD-L2 expression in tumor cells that in turn could weaken anticancer immunity." (PMID 35840558, 2022). "In addition, EZH2 is found to be up-regulated in CSCs that can enhance stemness of tumor CSCs." (PMID 36050791, 2022). "In this context, EZH2 inhibition activates a double-stranded RNA–STING–ISG stress response upregulating genes involved in antigen presentation, Th1 chemokine signaling, interferon response, the intratumoral trafficking of activated CD8+ T-cells, and increased M1 tumor-associated macrophages." (PMID 36135315, 2022). "Finally, these data demonstrate that the role of PIK3IP1 in the sensitivity of ARID1Adef cells to EZH2 inhibitors may be shared among multiple tumor types." (PMID 35852858, 2022). "However, inhibition of EZH2 had minimal impact on the growth of tumour cells." (PMID 36555253, 2022). "In addition, the relevance of EZH2 to tumor immune infiltration is uncertain in HCC." (PMID 35627262, 2022). "Similarly, LINC00511 could serve as an oncogene repressing cell apoptosis and accelerating tumour growth partially by epigenetically suppressing the expression of p57 through binding with EZH2." (PMID 35379783, 2022).
tumor (continued). "The EZH2 knockdown could enhance tumor response to immune checkpoint blockade therapy." (PMID 35912007, 2022). "Moreover, EZH2 inhibits tumor suppressor genes via methylation." (PMID 35625973, 2022). "The GSEA revealed that the genes correlated with PLCB1, including HEY1, EZH2, VEGFA, E2F3, and STC1, were enriched in angiogenesis, suggesting that the increased expression of PLCB1 might be associated with HCC recurrence via tumor-associated angiogenesis." (PMID 35707353, 2022). "The EZH2 (Enhancer of Zeste 2 polycomb repressive complex 2 subunit) gene encodes a protein of the PRC2 complex involved in proliferation, differentiation, ageing and maintenance of the chromatin structure through methylation, acting as both a tumour suppressor gene and an oncogene." (PMID 35626091, 2022). "Besides, EZH2 is responsible for preserving T-cell memory precursors in tumor suppression." (PMID 35236381, 2022). "Blocking this pathway may improve the anti-tumor effect of EZH2 inhibitors." (PMID 36038549, 2022). "Given that radiation paradoxically promotes tumor cell migration and invasion while exerting cytotoxic effects, we explored whether the EZH2/miR-138-5p axis plays an important part in inhibiting cell migration and invasion while augmenting cellular radiosensitivity." (PMID 36071871, 2022). "Various anticancer drugs are known to inhibit tumor cell division and induce cell death through cell cycle arrest, which prompted us to investigate whether the role of EZH2/miR-138-5p axis in enhancing radiosensitivity is facilitated by induced cell cycle arrest." (PMID 36071871, 2022). "In prostate cancer, EZH2 ablation also triggers an endogenous double-stranded RNA-STING axis-induced interferon response that enhances ICB therapy by increasing antigen presentation, Th1 chemokine signaling, and tumor infiltrations of activated CD8+ T cells and M1 tumor-associated macrophages." (PMID 35455671, 2022). "However, the tumor microenvironment can limit the conversion of oxidative phosphorylation to aerobic glycolysis by maintaining high expression of microRNA101 and microRNA26a, and limit the expression of EZH2 in T cells by controlling glucose metabolism." (PMID 36713412, 2022). "In hematopoietic stem and progenitor cells (HSPC), EZH2-inhibitors gave rise to increased NK precursors, leading to up-regulation of IL-15R (CD122) and NKG2D activated receptors, which were associated with enhanced NK cell expansion and cytotoxicity against tumor cells." (PMID 36313363, 2022). "Therefore, in TMA of GC, the tumor-promoting effect of FOXM1 and EZH2 in tumor cells may be correlated to the upregulation of FAP in CAFs." (PMID 36401232, 2022). "Therefore, we interrogated whether direct interaction of PRAME and EZH2 also occurred in DLBCL tumor cells." (PMID 35380993, 2022). "However, even within the same tumor entity, the molecular makeup of a tumor cell and/or hierarchical signalling cues converging on EZH2 significantly determine EZH2-dependent target gene regulation and hence critically affect the functional implications of the methyltransferase." (PMID 35884510, 2022). "Herein, we found that conditional deletion of both Ezh2 and Pten reduced cell proliferation and uterine growth during early carcinogenesis but exacerbated intraluminal neutrophil accumulation and chronic inflammation during tumor progression, leading to an unfavorable disease outcome." (PMID 35269532, 2022). "Loss of function in the tumour suppressor gene SNF5 (also known as SMARCB1, INI1, and BAF47), a subunit of the SNF/SWI complex, results in unopposed EZH2 activity and increased H3K27me3 levels which drive tumour growth in the absence of EZH2 gain of function mutations [7••]." (PMID 33937922, 2021). "In addition, EZH2 could also affect tumor progression via histone methyltransferase-related functions." (PMID 35059393, 2021).
tumor (continued). "EZH2 exhibits gene amplification and higher levels of expression in many human malignancies, such as gastric cancer, colon cancer, breast cancer, lymphoid hematopoietic tumors, liver cancer, and nephroblastoma, and is closely related to tumorigenesis and tumor progression." (PMID 33679454, 2021). "Interestingly, EZH2 may have a dual function, and based on the dynamic expression of EZH2 in cell differentiation and cell cycle progression, it has the ability to act as both an oncogene and a tumor suppressor." (PMID 34149432, 2021). "Moreover, EZH2 expression correlated with the tumor stages of patients with NSCLC." (PMID 33658396, 2021). "Therefore, EZH2 can function as a tumor suppressor or an oncogene in a context-dependent manner." (PMID 35054230, 2021). "Furthermore, the blockade of EZH2 suppressed GBM tumor growth." (PMID 34745848, 2021). "Therefore, we postulated that ZNF750 may be a crucial mediator on Ezh2, leading to reduced tumor growth, metastasis, and the E2F2 was involved in its regulation." (PMID 35003347, 2021). "In addition to the potential role of EZH2 inhibition in regulating tumor growth and metastasis, a recent preclinical study showed that targeting EZH2 may overcome anti-PD-1 resistance in HNSCC." (PMID 34680389, 2021). "In a whole, the results of this study not only indicate the great potential therapeutic effect of DZNep on bone defect, but also point out that the EZH2, in addition to an anti-tumor target, might be a momentous target in bone defect treatment by affecting osteoclast and osteoblast simultaneously." (PMID 34930462, 2021). "However, mutant STAT3 attenuated the effect of EZH2 knockdown on tumor growth to less extent." (PMID 34335938, 2021). "Conversely, the TMA was, by design, a homogeneous sampling of tumor epithelium where higher EZH2 expression may contribute to chemotherapy resistance through separate mechanisms – conceivably through immune-related pathways since TIL presence affected the prognostic significance." (PMID 34140011, 2021). "However, whether LINC02678 is involved in the regulation of tumor cell stemness and therapeutic resistance through binding potential with EZH2 demands further investigation." (PMID 34124072, 2021). "Numerous researchers have reported that EZH2 might serve as a tumor driver." (PMID 34666800, 2021). "However, despite multiple studies evaluating the association between overexpression of EZH2 or CHK1 and tumor chemoresistance and poor clinical outcomes, the interplay between these two regulators is largely unknown." (PMID 33408782, 2021). "In most studies, EZH2 inhibition could reduce tumor formation and promote cell death." (PMID 34512145, 2021). "Similarly, disruption of Ezh2 activity or depletion of Helios in Tregs leads to Foxp3 instability with an increased expression of effector cytokines like IFNγ and TNFα, enhanced anti-tumor immunity, and decreased tumor growth and progression." (PMID 34394124, 2021). "Finally, we assessed if pharmacologic inhibition of EZH2 may also affect the tumor microenvironment." (PMID 34857732, 2021). "Thus, although EZH2 might be a good target to restore tumor cell antigenicity and immunogenicity, pleiotropic effects should be studies, due to the various functions EZH2 might play with TME immune cell subsets." (PMID 33859645, 2021). "Therefore, more research on the combination of EZH2 inhibitors and tumour therapy has emerged." (PMID 33986254, 2021). "Similarly, inhibition of EZH2 in a PanNEN transgenic mouse model reduced tumor burden." (PMID 34638497, 2021). "In this regard, we now propose that stochastic dynamics of epigenetic switching suffices to dictate the emergence (and persistence) of tumor cell sub-populations with distinct degrees of responsiveness to EZH2 inhibitors in the absence of inactivating mutations of the EZH2 epigenetic partner KDM6A." (PMID 34153035, 2021).
tumor (continued). "Importantly, EZH2 and its inhibition might have different effects according to the tumor type and the immune infiltrate." (PMID 33859645, 2021). "Third, under the condition of chronic infection or tumor, EZH2 deficiency may not be conducive to a normal immune response." (PMID 34737746, 2021). "Interestingly, our conclusions on G9a activity and its relationship with pluripotency networks in CRC show similarities with another recent study relating EZH2 activity to hedgehog signaling, core pluripotency factors, and maintenance of tumor-initiating functions in CCSCs." (PMID 33323965, 2021). "Crucially, identification of non-mutational mechanisms capable of conferring EZH2 dependence to tumors could increase tumor and patient eligibility." (PMID 34153035, 2021). "In conclusion, we found that the expression of EZH2 depends upon complex interactions with immunologic pathways and local tumor microenvironment that alter its prognostic interpretation and may depend upon the subpopulation of tumor cells." (PMID 34140011, 2021). "However, the effect of EZH2 on DCs in tumor microenvironment still needs further investigation." (PMID 32723346, 2020). "Therefore, TET2 and EZH2 play a tumor-inhibiting role in AML that affects CIN via MAD2 and CDC20." (PMID 32066746, 2020). "However, despite this carcinogenic effect, other studies have suggested that EZH2 may also have an antitumor effect in some neoplasms since its inhibition favors tumor progression." (PMID 33053887, 2020). "Hence, the inactivation of Ezh2 impairs mouse GBM tumor growth and extends lifespan." (PMID 31934644, 2020). "Even though the highly expressed miR-144-3p can inhibit the EMT of tumor tissues and cells by targeting EZH2, PBX3, and MAP3K8, we found that EMT could be negatively regulated by miR-144-3p through the ROS/NRF2/Notch1/Snail pathway in high-glucose-stimulated LECs." (PMID 33274006, 2020). "Moreover, EZH2 and DNMT1 are negatively associated with tumor-infiltrating CD8+ T cells." (PMID 33031059, 2020). "Thus, inhibition of EZH2 activity by a small molecule inhibitor might be a potential approach to sensitize tumor cells to T cell-mediated anti-tumor immunity." (PMID 32787882, 2020). "We hypothesized that EZH2 and H3K27me3 as a silencer of tumor suppressor genes and a promoter of tumor growth and metastasis would be most active at the transition zone between tumor and surrounding stroma." (PMID 32041674, 2020). "EZH2 Tyr641 gain-of-function mutations were shown to increase H3K27 trimethylation, and this chromatin modification may be responsible for the silencing of tumor suppressor genes in mutated DLBCL cases." (PMID 32123491, 2020). "In summary, EZH2 might be an important factor of HER2+ BC progression and associated with a decrease in the overall survival of patients since EMT has been critically discussed as the key process in tumor aggressiveness and metastasis." (PMID 33014831, 2020). "In proliferating cells, many tumor-suppressor genes or senescence effectors are silenced by PRC2 (e.g., p16 and the CDKN2A gene at the INK4A locus), and in senescent cells, the transcriptional downregulation of EZH2 leads to a loss of H3K27me3 and the activation of PRC2-mediated genes." (PMID 32195249, 2020). "In a separate study comprised of 64 cases, EZH2 protein expression levels independently predicted worse recurrence-free survival and outperformed other known prognostic factors, such as Gleason score, tumor size and preoperative prostate-specific antigen (PSA) levels." (PMID 33050946, 2020). "In hematological malignancies, the role of EZH2 may be either oncogenic or tumor suppressive." (PMID 33003334, 2020). "In addition, we also found that GO could inhibit the cell viability and suppress the expression levels of H3K27me3 and EZH2 in U87 tumor cell, with a lower sensitivity than that of GSCs." (PMID 32410622, 2020).